ABCC6P2 (ATP binding cassette subfamily C member 6 pseudogene 2)
Gene: Transcribed unprocessed pseudogene on chromosome 16 (14,820,792 to 14,824,669, reverse strand). Ensembl gene ENSG00000255277.
Diseases named in the same sentence as ABCC6P2 in open-access papers:
ABCC6P2 is named in the same sentence as 2 diseases in open-access papers, as found by Europe PMC text mining. Sharing a sentence is not in itself a finding about the gene and the disease. The quoted sentences say what the papers report.
Pseudoxanthoma elasticum (1 paper, 2008). "Two pseudogenes, ABCC6P1 and ABCC6P2, have been reported for the pseudoxanthoma elasticum gene ABCC6, a member of the ABC C-subfamily." (PMID 18405356, 2008).
ABCC6P2 also shares sentences with these, for which no sentence is quoted: cancer (1 paper).